MIR635 (microRNA 635)
Synonyms: hsa-mir-635; MIRN635
Gene: MicroRNA gene on chromosome 17 (68,424,451 to 68,424,548, reverse strand). Ensembl gene ENSG00000207561.
Homologues: Orthologues: chimpanzee ptr-mir-635 (100% identical).